SNORA35B (small nucleolar RNA, H/ACA box 35B)
Gene: Small nucleolar RNA gene on chromosome X (115,126,316 to 115,126,444, reverse strand). Ensembl gene ENSG00000271907.
Gene Ontology:
Biological process: RNA processing
Cellular component: nucleolus
Homologues: Orthologues: macaque SNORA35B (99% identical), guinea pig SNORA35B (95% identical), rabbit SNORA35B (95% identical), mouse Gm25107 (93% identical), rat Snora35b (91% identical), pig SNORA35B (90% identical). Paralogues in human: SNORA35 (54% identical).